WDR3 (WD repeat domain 3)
Diseases named in the same sentence as WDR3 in open-access papers (continued):
Sharing a sentence is not in itself a finding about the gene and the disease.
schizophrenia (1 paper, 2018). A major psychotic disorder characterized by abnormalities in the perception or expression of reality. "In conclusion, our present associations study demonstrated that the WDR3 gene is selectively related to female schizophrenia." (PMID 29309433, 2018). "To further elucidate the molecular pathophysiology of schizophrenia, we have evaluated the genetic association of WDR3 and ALG1 in schizophrenia." (PMID 29309433, 2018). "Further study is required to elucidate the gender-dependent correlation between the WDR3 gene and schizophrenia using different ethnic populations and larger sample sizes." (PMID 29309433, 2018). "Genotyping and allele distribution of SNPs on WDR3 and ALG1 genes in schizophrenia and controls from the Japanese population." (PMID 29309433, 2018). "In the present study, we used single nucleotide polymorphisms (SNPs) in the Japanese case-control sample to implement a genetic association study of the WDR3 and ALG1 genes in schizophrenia." (PMID 29309433, 2018). "The best P-value was the combination of ALG1 SNP A9 (rs7195893) and WDR3 SNP W10 (rs1321666) in the female schizophrenia (P = 0.047), but the TA of this model was less than 0.55 (TA = 0.543)." (PMID 29309433, 2018). "In the female schizophrenia patients, WDR3 SNP W12 (rs10802003), ALG1 SNP A4 (rs3760030) and A7 (rs8045294) showed significant deviations from the HWE (P = 0.023, 0.026 and 0.024, respectively)." (PMID 29309433, 2018). "Therefore, we examined 11 SNPs of the human WDR3 gene and 10 SNPs of the human ALG1 gene as the genetic association study of schizophrenia." (PMID 29309433, 2018). "Therefore, WDR3 and ALG1 may also be associated with the susceptibility and/or pathogenesis of schizophrenia." (PMID 29309433, 2018). "Our findings suggest that the WDR3 gene may likely be a sensitive factor in female patients with schizophrenia, and that modification of the WDR3 signaling pathway warrants further investigation as to the pathophysiology of schizophrenia." (PMID 29309433, 2018). "This is the first genetic study of the WDR3 and ALG1 genes in schizophrenia to the best of our knowledge." (PMID 29309433, 2018). "Stratification analysis of sex on WDR3 and ALG1 gene in schizophrenia and controls from Japanese population." (PMID 29309433, 2018). "WDR3 SNP W4 (rs319471), W12 (rs10802003) and ALG1 SNP A7 (rs8045294) also displayed a tendency to genotypic association in the female subjects with schizophrenia compared to the female controls, however, it was not significant after multiple testing." (PMID 29309433, 2018).
cancer (8 papers, 2012 to 2025). A tumor composed of atypical neoplastic, often pleomorphic cells that invade other tissues. "OLFM (cTOH1) and WDR3 (cTOH2) have been implicated in apoptosis and cell cycle regulation in cancer cells." (PMID 22384118, 2012). "Additionally, several groups have also reported the biological role of WDR3 in modulating genome stability, increasing cancer predisposition, promoting proliferation and arresting cancer cells in the G1 phase of the cell cycle." (PMID 33648545, 2021). "Consequently, variations in the WDR3 function associated with the existence of genetic polymorphisms can generate genome instability that can result in an increased cancer risk." (PMID 23049746, 2012). "MTS, colony formation, and transwell assays were conducted to determine the biological role of WDR3 in human cancer." (PMID 33648545, 2021). "Here, WDR12, MYC, WDR3, are critical in the regulation of cell cycle progression in cancer cells." (PMID 34131166, 2021).
tumor (3 papers, 2021 to 2025). "Except WDR3, all the rest nine hub genes were significantly up-regulated in tumors when compared to tumor-adjacent normal tissues in both the TCGA_LIHC and GE64041 data sets." (PMID 34257542, 2021). "Consistent with this hypothesis, our study provides direct evidence that Nilotinib significantly inhibited the production of phase-separated condensates of WDR3, thereby suppressing tumor growth and metastasis in vivo and in vitro." (PMID 40646517, 2025). "In addition, sh-WDR3 transfection significantly reduced the positive area of WDR3 and Ki67 in mice tumor tissues, while promoting apoptosis, relative to controls." (PMID 40646517, 2025). "More importantly, mutation of WDR3 significantly down-regulated the proliferation and metastatic ability of U2-OS cells, but the transfection of MUT-IDR restored the malignant phenotype of tumor cells." (PMID 40646517, 2025). "Nilotinib may also reduce WDR3 phase-separated condensates and inhibit tumor growth and metastasis." (PMID 40646517, 2025).
WDR3 also shares sentences with these, for which no sentence is quoted: male infertility (1 paper).